CPEB3 (cytoplasmic polyadenylation element binding protein 3)
Diseases named in the same sentence as CPEB3 in open-access papers (continued):
Sharing a sentence is not in itself a finding about the gene and the disease.
neurodegenerative disease (1 paper, 2024). A disorder of the central nervous system characterized by gradual and progressive loss of neural tissue and neurologic function. "The study showed that CPEB3 plays a crucial role in memory storage, and it affects neuronal function when its expression is inhibited, suggesting that the CPEB3 protein could be a promising target for treating neurodegenerative diseases." (PMID 39771050, 2024).
CPEB3 also shares sentences with these, for which no sentence is quoted: prostate carcinoma (3 papers); bladder cancer (2); breast carcinoma (2); lung adenocarcinoma (2); pancreatic carcinomas (2); acute myeloid leukemia (1); adult T-cell leukemia (1); astrocytic tumor (1); colon cancer (1); liver disease (1); lymphoma (1); post-traumatic stress disorder (1); Premature ovarian insufficiency (1); renal carcinoma (1); serous ovarian cancer (1); temporal lobe epilepsy (1); type 2 diabetes (1).